BCHE (butyrylcholinesterase)
Description:
Esterase with broad substrate specificity. Contributes to the inactivation of the neurotransmitter acetylcholine. Can degrade neurotoxic organophosphate esters.
Synonyms: CHE1; E1; BCHED; CHE2
Tractability: Small molecule: an approved drug acts on it; a structure with a bound ligand is known; a high-quality ligand is known; it has a high-quality binding pocket; it belongs to a druggable protein family. Antibody: UniProt places it where antibodies can reach, with high confidence; its Gene Ontology location is reachable by antibodies, with high confidence; UniProt predicts a signal peptide or a membrane-spanning region. PROTAC: its protein half-life has been measured; a small molecule that binds it is known.
Target class: Enzyme; Hydrolase
Safety:
Unwanted effects reported when the protein is acted on. In parentheses: how it was acted on, where the effect was seen, and who reports it.
apnea (source: ClinPGx)
apnea following administration of succinylcholine (source: ClinPGx)
post anesthesia apnea (source: ClinPGx)
Gene: Protein-coding gene on chromosome 3 (165,772,904 to 165,837,462, reverse strand). Ensembl gene ENSG00000114200.
Subcellular location: Secreted
Pathways (Reactome):
Drug ADME: Aspirin ADME
Metabolism: Synthesis of PC
Metabolism of proteins: Synthesis, secretion, and deacylation of Ghrelin
Neuronal System: Neurotransmitter clearance
Gene Ontology:
Molecular function: cholinesterase activity; identical protein binding; protein binding; acetylcholinesterase activity; amyloid-beta binding; catalytic activity; enzyme binding; hydrolase activity, acting on ester bonds; choline binding
Biological process: acetylcholine catabolic process; choline metabolic process; cocaine catabolic process; peptide hormone processing; xenobiotic metabolic process; learning; negative regulation of cell population proliferation; negative regulation of synaptic transmission; neuroblast differentiation; response to alkaloid; response to folic acid; response to glucocorticoid; response to nutrient; response to xenobiotic stimulus
Cellular component: blood microparticle; extracellular region; plasma membrane; endoplasmic reticulum; endoplasmic reticulum lumen; nuclear envelope lumen
Genetic constraint (gnomAD): Loss-of-function variants: 48 observed, 51.08 expected, observed/expected ratio (o/e) 0.94, 90% interval 0.74 to 1.2. The upper end of that interval is the gene's LOEUF score, 1.2, which puts it in group 5 of 6, group 1 being the genes least tolerant of losing a copy. Missense variants: 822 observed, 727.88 expected, observed/expected ratio (o/e) 1.13, 90% interval 1.07 to 1.2. Synonymous variants: 248 observed, 248.27 expected, observed/expected ratio (o/e) 1, 90% interval 0.9 to 1.11.
Homologues: Orthologues: chimpanzee BCHE (99% identical), macaque BCHE (96% identical), rabbit BCHE (90% identical), dog BCHE (87% identical), guinea pig BCHE (83% identical), mouse Bche (80% identical), rat Bche (79% identical), tropical clawed frog bche (65% identical), Drosophila melanogaster Ace (38% identical), Caenorhabditis elegans ace-2 (35% identical). Paralogues in human: ACHE (51% identical), CES2 (31% identical), NLGN2 (31% identical), NLGN1 (30% identical), NLGN3 (30% identical), NLGN4X (30% identical), CEL (30% identical), NLGN4Y (30% identical), CES1 (29% identical), CES5A (29% identical), CES3 (28% identical), CES4A (28% identical), and 1 more.
Diseases named in the same sentence as BCHE in open-access papers:
BCHE is named in the same sentence as 227 diseases in open-access papers, as found by Europe PMC text mining. Sharing a sentence is not in itself a finding about the gene and the disease. The quoted sentences say what the papers report.
Alzheimer disease (363 papers, 2006 to 2026). A progressive, neurodegenerative disease characterized by loss of function and death of nerve cells in several areas of the brain leading to loss of cognitive function such as memory and language. "Cholinergic dysfunction is a hallmark of Alzheimer's disease (AD), driven by elevated acetylcholinesterase (AChE) and butyrylcholinesterase (BChE) activity that depletes acetylcholine and contributes to amyloid pathology." (PMID 41590732, 2026). "Alzheimer's disease (AD) is a common neurodegenerative disorder linked to cholinergic dysfunction, with butyrylcholinesterase (BChE) being a key therapeutic target for moderate-severe AD." (PMID 42197128, 2026). "Alzheimer’s disease (AD) is a neurodegenerative disorder categorized by the progressive loss of cognitive function, with acetylcholinesterase (AChE) and butyrylcholinesterase (BuChE) as key therapeutic targets." (PMID 40911700, 2025). "The results demonstrate that R. alba extracts (RAEs) possess significant inhibitory effects on enzymes implicated in neurodegenerative disorders, such as Alzheimer’s disease, particularly through butyrylcholinesterase inhibition." (PMID 41393958, 2025). "The inhibitory interaction of BMB with the butyrylcholinesterase enzyme, which is a major cause of dementia and Alzheimer’s disease, has been investigated based on molecular modelling." (PMID 40542029, 2025). "BChE has also been implicated in compensatory mechanisms during neurodegenerative processes, particularly in Alzheimer’s disease (AD)." (PMID 41322300, 2025). "Lupeol, a naturally occurring triterpenoid, has demonstrated notable inhibitory activity against BChE, an enzyme implicated in neurodegenerative disorders like Alzheimer’s disease." (PMID 40661854, 2025). "High levels of BChE have been found to be associated with brain plaques and neurofibrillary tangles, which are neuropathological features of Alzheimer’s disease (AD)." (PMID 40871591, 2025). "Cachrys sicula L. (Apiaceae) EO effectively inhibits key enzymes associated with Alzheimer’s disease, particularly butyrylcholinesterase (BChE)." (PMID 40979172, 2025). "This plant extract's inhibition of AChE and BChE enzymes indicates its potential to preserve brain function and mitigate the risk of Alzheimer's disease." (PMID 39698089, 2024). "Acetylcholinesterase (AChE) and butyrylcholinesterase (BChE) are the critical enzymes implicated in β-amyloid accumulation, a process associated with Alzheimer’s disease and other neurodegenerative disorders." (PMID 39771165, 2024). "The aggregation of proteins, tau oligomers and amyloid-β oligomers, acetylcholine, and butyrylcholinesterase are considered the main cause of mitochondrial dysfunction, producing neuronal toxicity resulting in Alzheimer’s disease." (PMID 38673848, 2024). "Regarding neuroprotection, the extracts demonstrated significant inhibition of butyrylcholinesterase and acetylcholinesterase, enzymes linked to Alzheimer’s disease." (PMID 39351095, 2024). "The cholinergic dysfunction, marked by exacerbated cholinesterase activities (AChE and BChE), is well recognized in Alzheimer's disease (AD), the most prevalent cause of dementia." (PMID 38539199, 2024). "Aggregation of proteins, tau oligomers and amyloid-beta oligomers, acetylcholine, and butyrylcholinesterase are considered the main cause of mitochondrial dysfunction, producing neuronal toxicity and resulting in Alzheimer’s disease." (PMID 38673848, 2024). "Previous studies have shown that high BChE can cause disrupted neurotransmission in Alzheimer’s disease; however, it remains unexplored as a target for brain cancer." (PMID 37637064, 2023). "The inhibition of key enzymes linked to Alzheimer’s disease (AD), such as acetylcholinesterase (AChE) and butyrylcholinesterase (BChE), is an important task for identifying novel and safe medicine from natural sources, especially those found in native plants." (PMID 36840166, 2023).
Alzheimer disease (continued). "The peptidase activity of butyrylcholinesterase is important because it is believed to be involved in the development and progression of Alzheimer’s disease, as it is a causative factor in the production of β-amyloids." (PMID 35630702, 2022). "The decreasing impact on the Alzheimer’s disease risk correlates with its inhibition effects against the acetylcholinesterase (AChE) and butyrylcholinesterase (BChE)." (PMID 35558110, 2022). "Butyrylcholinesterase (BuChE) also causes the inactivation of acetylcholine (ACh) neurotransmitters and can be targeted therapeutically in Alzheimer’s disease." (PMID 35741617, 2022). "The study aimed to investigate in-vitro neuroprotective effect of the plant extracts through testing against acetylcholinesterase (AChE), butyrylcholinesterase (BChE), and β-secretase linked to Alzheimer’s disease (AD)." (PMID 36686717, 2022). "Pharmacological inhibition of cholinesterase (ChE) enzymes (acetylcholinesterase (AChE) and/or butyrylcholinesterase) is the most common treatment for Alzheimer’s disease (AD) and its associated complications." (PMID 35372507, 2022). "Acetylcholinesterase (AChE, EC 3.1.1.7) and butyrylcholinesterase (BChE, EC 3.1.1.8) are enzymes associated with the pathology of Alzheimer’s disease (AD)." (PMID 34371671, 2021). "Certain green, red, orange, and yellow pepper showed interesting capacity to inhibit some key enzymes linked to Alzheimer disease [acetylcholinesterase (AChE), butyrylcholinesterase (BChE), and β-secretase (BACE1)]." (PMID 32604812, 2020). "A meta-analysis based on 56 genetic case-control studies of 12,563 cases and 12,622 controls associated the BCHE gene with Alzheimer’s disease." (PMID 30591010, 2018). "The presence of the K variant of BChE is controversially considered a risk factor for Alzheimer disease (AD)." (PMID 29358722, 2018). "Herein, substances 1 and 2 were reisolated and assayed for the inhibitory activity of human recombinant acetyl (Hr-AChE) and human serum butyrylcholinesterase (Hu-BChE) enzymes, key therapeutic and diagnostic targets for Alzheimer's disease." (PMID 29291077, 2017). "Meanwhile, BChE has been considered to be directly associated with the side effects of the AChE inhibitors and the existing drugs of Alzheimer's disease." (PMID 25506036, 2014). "Apart from the many other reasons for Alzheimer's disease, its association with the genesis of fibrils by β-amyloid plaques is closely related to the increased activity of butyrylcholinesterase." (PMID 20550720, 2010). "Considering that butyrylcholinesterase was associated with both type 2 diabetes mellitus and with Alzheimer's disease, and that leads existed for the a role of butyrylcholinesterase in their pathogeneses, we chose it as the reference protein." (PMID 17096857, 2006). "The association of BchE K variant in both Alzheimer's disease and type 2 diabetes mellitus suggests a possible pathogenic role in both diseases." (PMID 17096857, 2006). "Alzheimer's disease, the leading cause of dementia, is strongly associated with impaired cholinergic neurotransmission due to excessive acetylcholine degradation by acetylcholinesterase (AChE) and butyrylcholinesterase (BChE)." (PMID 41813747, 2026). "Alzheimer’s disease is one of the most common progressive neurodegenerative disorders related to a deficiency of acetylcholine and butyrylcholine, which are hydrolyzed by AChE and BChE, respectively." (PMID 39202972, 2024). "Decreases in the neurotransmitter levels in the cholinergic synapses within certain regions of the brain are caused by acetylcholine and butyrylcholine hydrolysis, caused by AChE and BChE; therefore, their inhibition by these compounds is a suitable therapy for Alzheimer’s disease." (PMID 38893333, 2024).
Alzheimer disease (continued). "In previous studies, it has been reported that antioxidant molecules inhibit acetylcholinesterase (AChE), butyrylcholinesterase (BChE), and carbonic anhydrase (CA) enzymes, which are linked to some common diseases including epilepsy, glaucoma, and Alzheimer’s disease (AD)." (PMID 36986640, 2023). "Additionally, EDOA and EDOR were tested against enzymes such as acetylcholinesterase, butyrylcholinesterase, and α-glycosidase, which are associated with common diseases such as diabetes, Alzheimer’s disease, and glaucoma." (PMID 36296499, 2022). "The inhibition effect of Magnofluorine was examined against enzymes, such as acetylcholinesterase (AChE), α-glycosidase, butyrylcholinesterase (BChE), and human carbonic anhydrase II (hCA II), which are linked to global disorders, such as diabetes, Alzheimer’s disease (AD), and glaucoma." (PMID 36144638, 2022). "Butyrylcholinesterase (BChE) is widely distributed in plasma, liver, muscle and brain tissues and is associated with lipid metabolism and various human diseases such as liver injury, diabetes, Alzheimer’s disease (AD) and liver metastasis." (PMID 35889374, 2022). "Degradation of neurotransmitters by cholinesterases (ChEs), including acetylcholinesterase (AChE) and butyrylcholinesterase (BChE), have been hypothesized as a cause of Alzheimer’s disease (AD) occurrence." (PMID 33670795, 2021). "Butyrylcholinesterase (BChE) is detected in plaques preferentially in Alzheimer’s disease (AD) and may be associated with stress disorders." (PMID 34062954, 2021). "This seed showed potential as functional food/or nutraceuticals in the management of neurodegenerative diseases such as Alzheimer's disease as it exhibited inhibitory activity on key enzymes (acetylcholinesterase and butyrylcholinesterase) linked to this disease." (PMID 25506036, 2014). "Neurologically associated disability, such as Parkinson’s disease, Alzheimer’s disease (AD), and other cognitive losses, is due to defective cholinergic neurotransmission, caused by the lytic action of acetylcholinesterase (AChE) and butyrylcholinesterase (BChE)." (PMID 41304978, 2025). "Patients with Alzheimer’s disease (AD) have two types of abnormal protein buildups: amyloid plaques and neurofibrillary tangles, in addition to the early synaptic dysfunction associated with the enzymes acetylcholinesterase (AChE) and butyrylcholinesterase (BuChE)." (PMID 40056267, 2025). "Additionally, the inhibition effects of Schiff bases and hydrazineylidene derivatives (16 and 17) were determined against some metabolic enzymes including AChE, BChE, hCA I, and hCA II enzymes, which are linked to some global disorders including Alzheimer’s disease (AD), epilepsy, and glaucoma." (PMID 36986640, 2023). "Additionally, Magnofluorine was tested against some metabolic enzymes, including acetylcholinesterase, α-glycosidase, butyrylcholinesterase, and carbonic anhydrase isoform II, which are linked to some common and global diseases, such as epilepsy, diabetes, Alzheimer’s disease, and glaucoma." (PMID 36144638, 2022). "Four colors of sweet peppers (green, yellow, orange, and red) exert antioxidant activities and inhibitory effects on Alzheimer’s disease-associated key enzymes, such as acetylcholinesterase, butyrylcholinesterase, and β-secretase, and thereby may be useful for the prevention of Alzheimer’s disease." (PMID 36234931, 2022). "In addition, previous studies have also found that the cholinergic enzyme is linked to Alzheimer’s disease, and the inhibition of cholinergic enzymes such as acetylcholinesterase (AChE) and butyrylcholinesterase (BChE) has been recognized as an acceptable treatment for this disease." (PMID 36234873, 2022). "These would help proffer a solution to the menace of ‘Alzheimer’s disease caused by the overexpression and dysregulation of AChE and BChE, which could subsequently serve as a corrective measure to the degree of alteration and mutation of proteins at the neuromuscular junction." (PMID 34592924, 2021).
Alzheimer disease (continued). "Causes of Alzheimer’s disease (AD), one type of dementia, have been attributed to (i) degradation of the neurotransmitter acetylcholine by acetylcholinesterase (AChE) and butyrylcholinesterase (BChE), or (ii) accumulation of amyloid plaque formed during amyloidogenesis by β-secretase (BACE-1)." (PMID 34451608, 2021). "The extract's inhibitory effects on key enzymes like acetylcholinesterase (AChE), butyrylcholinesterase (BChE), and α‐glycosidase were evaluated due to their relevance in metabolic and neurodegenerative disorders such as diabetes and Alzheimer's disease." (PMID 40501503, 2025). "Potential anti-Alzheimer’s disease capacity was evaluated by AChE and BChE enzyme inhibition assays." (PMID 40868920, 2025). "This study successfully identified two promising BChE inhibitors with anti-Alzheimer’s disease (AD) potential." (PMID 40430266, 2025). "(Z)-13-Docosenamide bound human butyrylcholinesterase with higher affinity, supporting its candidacy as an inhibitor relevant to neurological disorders including Alzheimer’s disease." (PMID 41153994, 2025). "Alzheimer Disease (AD) - BChE complements AChE activity in the central nervous system by breaking down ACh and maintaining cholinergic signaling." (PMID 40612057, 2025). "By inhibiting key enzymes like acetylcholinesterase (AChE), butyrylcholinesterase (BChE), and glycogen synthase kinase-3β (GSK-3β), they help prevent the formation of β-amyloid plaques, a hallmark of Alzheimer’s disease." (PMID 40333636, 2025). "In Alzheimer’s disease, BChE activity increases during advanced stages, while acetylcholinesterase (AChE) levels decline markedly, suggesting a compensatory mechanism in cholinergic signaling and cognitive function." (PMID 40678419, 2025). "Cholinesterases such as acetylcholinesterase (AChE) and butyrylcholinesterase (BuChE) are established drug targets for treatment of Alzheimer’s disease." (PMID 41103911, 2025). "Alginate has a neuroprotective role and has an inhibition capacity for high expression levels of butyrylcholinesterase (BChE) in advanced Alzheimer’s disease." (PMID 41304964, 2025). "Butyrylcholinesterase and neuroinflammation represent promising therapeutic targets for Alzheimer’s disease (AD)." (PMID 40507988, 2025). "In particular, the dual action of statins and the effects of BChE on lipid metabolism and the neurological system offer new strategies for the prevention or treatment of Alzheimer’s disease and other neurodegenerative disorders." (PMID 40116876, 2025). "Alzheimer’s disease is characterized by high levels of BChE activity in the later stages as a compensatory mechanism for downregulating the activity and function of acetylcholinesterase (AChE)." (PMID 41304964, 2025). "Butyrylcholinesterase, as well as acetylcholinesterase, play a crucial role in the progression of Alzheimer’s disease." (PMID 39996817, 2025). "Monoamine oxidase B (MAO-B), acetylcholinesterase (AChE), and butyrylcholinesterase (BChE) are important targets for drugs used in the treatment of Alzheimer’s disease." (PMID 39859562, 2025). "In animal models of Alzheimer’s disease, plant sterols (β-sitosterol and stigmasterol) improve cognitive function by reducing acetylcholinesterase or acetylcholinesterase (AChE/BChE) activity and free radical load in the cerebral cortex and hippocampus." (PMID 41009787, 2025). "In Alzheimer’s disease, while AChE activity decreases in the hippocampus and temporal cortex, the action of BChE increases in these regions, highlighting the significant role of BChE in regulating brain acetylcholine levels." (PMID 40143145, 2025). "Butyrylcholinesterase and α-amylase are essential targets for drugs and extracts because their inhibition is involved in the management of Alzheimer’s disease (AD) and diabetes mellitus (DM)." (PMID 40872119, 2025).